OR7D4 (olfactory receptor family 7 subfamily D member 4)
Description:
Odorant receptor. Selectively activated by androstenone and the related odorous steroid androstadienone.
Synonyms: OR7D4P; hg105; OR19-B; OR19-7; OR19B
Tractability: Antibody: its Gene Ontology location is reachable by antibodies, with high confidence; UniProt places it where antibodies can reach, with medium confidence; UniProt predicts a signal peptide or a membrane-spanning region.
Gene: Protein-coding gene on chromosome 19 (9,210,276 to 9,219,589, reverse strand). Ensembl gene ENSG00000174667.
Subcellular location: Cell membrane
Pathways (Reactome):
Sensory Perception: Expression and translocation of olfactory receptors; Olfactory Signaling Pathway
Gene Ontology:
Molecular function: protein binding; olfactory receptor activity; G protein-coupled receptor activity
Biological process: signal transduction; detection of chemical stimulus involved in sensory perception of smell; G protein-coupled receptor signaling pathway
Cellular component: plasma membrane; membrane
Genetic constraint (gnomAD): Loss-of-function variants: 0 observed, 0.12 expected, observed/expected ratio (o/e) 0, 90% interval 0 to 1.89. That is too few expected variants to judge how well the gene tolerates losing a copy. Missense variants: 319 observed, 386.42 expected, observed/expected ratio (o/e) 0.83, 90% interval 0.75 to 0.91. Synonymous variants: 154 observed, 160.76 expected, observed/expected ratio (o/e) 0.96, 90% interval 0.84 to 1.1.
Homologues: Orthologues: chimpanzee OR7D4 (98% identical), macaque OR7D4 (92% identical), mouse Or7d9 (78% identical), rat Or7d9 (76% identical), mouse Or7d11 (72% identical), mouse Or7d10 (71% identical), rat Or7d11c (70% identical), rat Or7d10 (70% identical). Paralogues in human: OR7A5 (68% identical), OR7C2 (68% identical), OR7D2 (68% identical), OR7A17 (68% identical), OR7A10 (67% identical), OR7C1 (66% identical), OR7E24 (65% identical), OR7G3 (64% identical), OR7G2 (62% identical), OR7G1 (59% identical), OR1F1 (55% identical), OR1G1 (54% identical), and 116 more.
Diseases named in the same sentence as OR7D4 in open-access papers:
OR7D4 is named in the same sentence as 2 diseases in open-access papers, as found by Europe PMC text mining. Sharing a sentence is not in itself a finding about the gene and the disease. The quoted sentences say what the papers report.
Anosmia (1 paper, 2025). An inability to perceive odors. "In conclusion, it appears that the ability to perceive androstenone can be trained in people with specific anosmia, although OR7D4 polymorphisms were not related to a major change in the sensitivity towards androstenone." (PMID 40687083, 2025). "In addition, OR7D4 genotype had no significant impact on the outcome of OT in subjects with specific anosmia to androstenone." (PMID 40687083, 2025).
OR7D4 also shares sentences with these, for which no sentence is quoted: cancer (1 paper).